INS (insulin)
Diseases named in the same sentence as INS in open-access papers (continued):
Sharing a sentence is not in itself a finding about the gene and the disease.
Impaired glucose tolerance (continued). "Consistently, we also observed systemic IR phenotypes in HFD mice, including increased blood glucose, elevated blood lipids, impaired glucose tolerance, and diminished insulin sensitivity." (PMID 38599845, 2024). "Rats exposed to PFOS during gestation exhibited pre-diabetic symptoms in their offspring, with elevated fasting insulin and leptin levels and impaired glucose tolerance compared to the control group." (PMID 38393000, 2024). "Previous studies have reported that lower insulin secretion index and impaired insulin sensitivity in older adults as compared with younger individuals contribute to impaired glucose tolerance in older adults." (PMID 38188453, 2024). "While the impaired glucose tolerance observed here is consistent with a previous report, insulin sensitivity was enhanced only in male KOs and unchanged in female mice." (PMID 39568151, 2024). "Collectively, the 1-month metabolic tests in females suggested that LivARKO was able to prevent HFD-induced impaired glucose tolerance and improved insulin sensitivity." (PMID 38425436, 2024). "Based on these results, we concluded that MLL+/− mice exhibit impaired glucose tolerance and reduced insulin secretion, in line with our data from βHC-9 cells." (PMID 38731926, 2024). "Previous studies showed that sleep deprivation can lead to impaired glucose tolerance and reduced insulin sensitivity." (PMID 39056724, 2024). "One of the major studies, involving 5677 subjects with impaired glucose tolerance, showed that vitamin D supplementation increased insulin sensitivity by 54%." (PMID 36839279, 2023). "Significantly elevated (p < 0.05) levels of plasma insulin and impaired glucose tolerance were observed in PCOS rats in addition with increased blood glucose levels when compared to control." (PMID 37789355, 2023). "What is the most beneficial exercise strategy for improving insulin and glucose homeostasis in individuals with impaired glucose tolerance compared with those with established T2D?" (PMID 37259917, 2023). "Afmid-knockout mice exhibit impaired glucose tolerance with unchanged insulin sensitivity, suggesting involvement of arylformamidase in glucose-induced insulin secretion." (PMID 36766803, 2023). "Upon closer examination of glucose uptake rates within key insulin-sensitive tissues, we detected that the white ATs played a pivotal role in the manifestation of impaired glucose tolerance observed in Atg5eoΔ mice." (PMID 38235134, 2023). "In support of the insulin–resistant role of Fetuin–B, there are also animal studies showing that mice treated with Fetuin–B develop impaired glucose tolerance." (PMID 37274345, 2023). "Although many of the mice fed a HFD for 4 weeks exhibited elevated body weights, impaired glucose tolerance and insulin sensitivity, a subset of mice in our study still exhibited only elevated body weights with normal glucose tolerance and insulin sensitivity." (PMID 37884540, 2023). "KSR2 interacting with AMPK play significant roles in high insulin level and impaired glucose tolerance which can explain this phenomenon." (PMID 37334291, 2023). "Progression from early to late adulthood is commonly accompanied by an impaired glucose metabolism, including increased plasma insulin levels and impaired glucose tolerance." (PMID 36735680, 2023). "Some of the negative outcomes of an oxidative environment that promotes the development of T2D are impaired glucose tolerance, impaired insulin signaling, β-cell dysfunction, and mitochondrial dysfunction." (PMID 37237860, 2023). "In other words, an intervention study by long-term autophagy inhibition showed impaired glucose tolerance, diminished insulin content, and growth of islet-cell cysts in β cells." (PMID 37189396, 2023). "PRLR knockout (Prlr-) mice developed impaired glucose tolerance, decreased insulin secretion, a 20-35% reduction in islet insulin granules, reduced islet density and reduced β-cell mass." (PMID 36993818, 2023).
Impaired glucose tolerance (continued). "Their findings revealed that humans with normal and impaired glucose tolerance exhibited a substantial and prolonged insulin response, with peak concentrations exceeding 11-fold basal levels and remaining elevated for at least 150 minutes." (PMID 38134122, 2023). "In Fiorentino’s study, subjects had been chosen from a population with different degrees of insulin sensitivity, including normal glucose tolerance, impaired glucose tolerance, impaired fasting glucose, and patients with T2D." (PMID 37161502, 2023). "Both depletion of platelets and ablation of major platelet adhesion or activation pathways consistently resulted in impaired glucose tolerance and decreased circulating insulin levels." (PMID 37490001, 2023). "Impaired glucose tolerance upon M5 tanycyte depletion was accompanied by improved insulin sensitivity but decreased plasma insulin levels." (PMID 36949050, 2023). "VAT aging is associated with structural remodeling (i.e., enlargement of adipocytes, fibrotic deposition), metabolic dysfunction (i.e., impaired glucose tolerance, insulin sensitivity, and adipokine secretion), and senescence." (PMID 37092554, 2023). "Another study showed that maternal exposure to 3 ppm iAs from prenatal stages to 4 months old damaged pancreatic β cells, reduced insulin secretion, and impaired glucose tolerance in F1 female rats." (PMID 37691128, 2023). "When the offspring were further subjected to metabolic stress, these GDM offspring had a reduced insulin secretion index with impaired glucose tolerance." (PMID 37855321, 2023). "In 2010, it was shown that BPA exposure as low as 10 μg/kg/day decreased insulin sensitivity, impaired glucose tolerance, and increased plasma concentrations of insulin, triglycerides, and leptin in dams." (PMID 37134142, 2023). "Acute chemogenetic M5 tanycyte activation induces insulin secretion and acute diphtheria toxin-mediated M5 tanycyte depletion results in impaired glucose tolerance in mice." (PMID 36949050, 2023). "Meanwhile, 10% bean leaves supplementation (HBL) prevented impaired glucose tolerance, hypercholesterolemia, and improved insulin resistance due to less body fat accumulation." (PMID 37447254, 2023). "Lipid free apoA-I increases glucose uptake in mouse skeletal muscle and has a role in regulating insulin sensitivity in subjects with impaired glucose tolerance." (PMID 38008260, 2023). "Iron overload induces MIN6 cell dysfunction, leading to increased fasting blood glucose, impaired glucose tolerance, and significantly decreased insulin sensitivity in mice." (PMID 37090106, 2023). "The discordant behaviour of impaired glucose tolerance alongside improved insulin sensitivity in PLX5622-treated mice suggested that CSF1R inhibition affected beta cell function." (PMID 37792013, 2023). "A high-fat diet with TMAO precursors activates impaired glucose tolerance and inhibits the hepatic insulin signaling pathway." (PMID 37111261, 2023). "After nine weeks of exposure, we observed higher fasting blood glucose and impaired glucose tolerance, whereas insulin sensitivity was slightly improved compared to vehicle-WT." (PMID 37383489, 2023). "The decreased serum insulin levels in response to glucose accounted for the impaired glucose tolerance." (PMID 37914684, 2023). "This differs from the impaired glucose tolerance and threefold increase in insulin secretion required to adapt to the glucose challenge in HF235-fed mice receiving a vehicle." (PMID 36918710, 2023). "This situation suggested that β-cells tried to overcome the age-dependent development of impaired glucose tolerance, decreased insulin sensitivity, and elevated IR." (PMID 36834922, 2023). "In another crossover study, the consumption of soybeans fermented by B. natto in overweight individuals with impaired glucose tolerance improved insulin sensitivity and oxidative stress and significantly reduced total and LDL-C levels." (PMID 37139448, 2023).
Impaired glucose tolerance (continued). "Compared to both controls, male TH mice with T2DM exhibited higher blood glucose levels, weight along with impaired glucose tolerance and insulin sensitivity." (PMID 38130754, 2023). "They found that patients with IPAH had impaired glucose tolerance and reduced glucose-stimulated insulin secretion compared with matched controls." (PMID 37443009, 2023). "Forty-one percent of Endocrinologists surveyed (9/22) usually or sometimes start insulin on a patient with impaired glucose tolerance/prediabetes." (PMID 37274323, 2023). "Only the lowest dose of 50 μg/kg of BPA produced effects such as increased body weight, elevated serum insulin and impaired glucose tolerance in adult pups." (PMID 36902016, 2023). "A study of 32 cats of varying body weights, including 7 with impaired glucose tolerance, found that fasting insulin concentration and HOMA were useful overall predictors of insulin sensitivity and resistance." (PMID 35968003, 2022). "When male mice were exposed to twelve weeks of voluntary wheel-running, their resulting progeny were more susceptible to the adverse effects of HFD as demonstrated by increased body weight, adiposity, impaired glucose tolerance, and elevated insulin levels." (PMID 35466187, 2022). "A previous study revealed that GIPR(-/-) mice had impaired glucose tolerance and significantly reduced insulin gene expression and secretion compared with wild-type mice." (PMID 36860432, 2022). "Both Cre lines target β-cell expression, and both models showed defects in in vivo and in vitro glucose-stimulated insulin secretion, reduced serum insulin levels, and impaired glucose tolerance." (PMID 35813631, 2022). "Telehealth-based RET is feasible in adolescents with CF and impaired glucose tolerance and elicits small yet favorable changes in insulin secretion, body composition, and exercise capacity." (PMID 35328985, 2022). "In diet-induced obesity (DIO) mouse model, niacin treatment resulted in elevated blood glucose, impaired glucose tolerance and insulin secretion, accompanied by the change of islets morphology and the decrease of β cell mass." (PMID 36568082, 2022). "We previously showed that mice fed an HFD had significantly increased body weight and fat pad weight, impaired glucose tolerance, and reduced insulin sensitivity compared to mice fed a low-fat diet." (PMID 36295815, 2022). "SIRT1−/− animals exhibited increased fat mass, impaired glucose tolerance, and attenuated insulin sensitivity." (PMID 35721807, 2022). "LBP not only markedly restored the impaired glucose tolerance but also improved the insulin tolerance in diabetic mice." (PMID 35845787, 2022). "ZDF rats were previously found to have elevated fasting serum glucose, insulin, cholesterol and triglyceride levels as well as impaired glucose tolerance." (PMID 36013400, 2022). "Progeny of males subjected to wheel-running for twelve weeks produced offspring that were more susceptible to the adverse effects of HFD (increased body weight, adiposity, impaired glucose tolerance, and elevated insulin levels)." (PMID 35466187, 2022). "Genetic polymorphism in PPARD (rs2267668; A/G: PPARD-2) has also been described to affect insulin sensitivity and the conversion from impaired glucose tolerance to T2DM." (PMID 35205333, 2022). "Mice with β cell-specific deficiency of autophagy show degenerated β cells, hyperglycemia, reduced insulin release, and impaired glucose tolerance." (PMID 35327565, 2022). "Haploinsufficiency of Mll2 led to hyperglycemia and hyperinsulinemia at fasting and impaired glucose tolerance, and blunted insulin secretion in response to glucose loading." (PMID 34984701, 2022). "They showed that TNF-α positively correlated with FPG and fasting plasma insulin in normal glucose tolerance and impaired glucose tolerance subjects." (PMID 36140983, 2022).
Impaired glucose tolerance (continued). "The adult mice showed small and disorganized islets, decreased insulin production, reduced glucose-stimulated insulin section, and impaired glucose tolerance." (PMID 35832432, 2022). "We demonstrated that mice with germline haploinsufficiency of IGF-1 R have enhanced insulin-mediated glucose lowering with impaired glucose tolerance." (PMID 35734881, 2022). "Several studies investigating people with CF with impaired glucose tolerance reported low early-phase and high late-phase insulin secretion." (PMID 35529332, 2022). "Decreased insulin sensitivity was manifested by increased fasting glucose and insulin levels, impaired glucose tolerance, decreased insulin sensitivity, and increased HOMA-IR." (PMID 35406688, 2022). "We observed that both impaired glucose tolerance and insulin tolerance by simvastatin treatment were improved by GGOH." (PMID 35961942, 2022). "Consistent with changes in body composition, HFCON mice exhibit impaired glucose tolerance (p < 0.05), increased fasting blood glucose (p < 0.05), and increased serum insulin (p < 0.05) as compared to CON mice." (PMID 35393401, 2022). "The present study investigated the effect of apple consumption on postprandial blood glucose and insulin levels in subjects with normal versus impaired glucose tolerance." (PMID 35742001, 2022). "It is known that diabetic patients with impaired glucose tolerance are often compromised in insulin secretion." (PMID 36569345, 2022). "A low-potassium diet can lead to the development of impaired glucose tolerance, through impairments in insulin secretion from pancreatic β-cells." (PMID 35694169, 2022). "Regardless of the genotype, exposure to HFD resulted in the significant increase in weight gain, glycemia, as well as in impaired glucose tolerance and insulin sensitivity." (PMID 35707720, 2022). "Consistently, elevated glucose levels, impaired glucose tolerance, reduced insulin levels, decreased plasma levels of GLP-1, and downregulated mRNA expression of ileal Gcg were observed in MMI mice compared to untreated control mice (CT mice)." (PMID 36302774, 2022). "Accordingly, the HFDS mice presented impaired glucose tolerance, higher body fat mass, reduced caloric intake, and insulin sensitivity in the present study." (PMID 35669687, 2022). "With the six-week GYY4137 treatment, impaired glucose tolerance and reduced insulin sensitivity in MCSEKO mice were significantly reversed." (PMID 36358588, 2022). "Infertile women with PCOS had a higherBMI and waist circumference, elevated hsCRP and uric acid (UA) levels, impaired glucose tolerance, and increased levels of plasma insulin compared to UI patients and healthy women." (PMID 36157441, 2022). "A retrospective analysis from Japan found that young women with underweight status were more likely to show impaired glucose tolerance, which was characterized by impaired early insulin secretion and insulin insensitivity." (PMID 36291808, 2022). "According to our results, LWE intervention decreased visceral fat accumulation and adipocyte size, with subsequent improvements in impaired glucose tolerance and insulin sensitivity." (PMID 35681388, 2022). "Short-term ‘high-protein and low-carbohydrate’ diets decreased insulin sensitivity, impaired glucose tolerance, and increased triglycerides, resulting in metabolic dysregulation." (PMID 35276838, 2022). "As expected, HFD-fed mice displayed impaired glucose tolerance and decreased insulin, as well as an evident increase in the fasting blood glucose and blood glucose at 0.5 h after meal as compared to control mice." (PMID 35573781, 2022). "The exacerbation in impaired glucose tolerance was probably triggered by TMAO-aggravated blockage of the insulin signalling cascade." (PMID 35631234, 2022). "Many patients progress from nonmedical, lifestyle-only treatment to medications like metformin, and some require insulin as their condition shifts from impaired glucose tolerance to insulin insufficiency." (PMID 35559025, 2022).
Impaired glucose tolerance (continued). "The diminished AUC further proved that SFG supplementation enhanced insulin sensitivity, allowing glucose to translocate from the blood into the cells more efficiently, thus improving the impaired glucose tolerance in db/db mice." (PMID 35893259, 2022). "At 3 months, male βTGS1KO mice exhibit an increase in fed glucose and decrease in insulin and impaired glucose tolerance after glucose challenge." (PMID 35041827, 2022). "Impaired glucose tolerance, decreased insulin responsiveness and an increase in the HOMA-IR values were also observed compared with the control LFD group." (PMID 35406688, 2022). "The deletion of Prmt5 in mice leads to reduced insulin expression, impaired glucose tolerance, and glucose‐stimulated insulin secretion (GSIS) through histone methylation‐related chromatin remodelling." (PMID 34984701, 2022). "Meanwhile, the HS diet also resulted in impaired glucose tolerance and blunted insulin secretion upon glucose stimulation." (PMID 34085773, 2021). "For example, long-term exposure to PM2.5 in C57BL/6 mice resulted in impaired glucose tolerance and resistance to insulin." (PMID 34745386, 2021). "Previous research confirms this argument, they found that autophagy-related (ATG) 7 knockout mice showed decreased β-cell mass through increased apoptosis, which ultimately lead to decreased insulin secretion and impaired glucose tolerance." (PMID 34356312, 2021). "Expected T2D phenotypes were observed in both male and female diabetic mice, including high body weight, increased fasting insulin levels, and impaired glucose tolerance." (PMID 34571259, 2021). "The knockdown of Glut4 in the mouse brain leads to impaired glucose tolerance, reduced insulin sensitivity, and impaired glucose-lowering regulation in mice." (PMID 34733235, 2021). "High-fat diet-fed SIRPα-/- mice exhibit reduced plasma insulin levels and impaired glucose tolerance as compared to wild-type mice, providing in vivo evidence that SIRPα can control insulin secretion in the context of metabolic stress." (PMID 34603322, 2021). "Metabolomic profiling reveals that a glucose ingestion in fasted individuals elicits an insulin-dependent metabolic response, which is blunted in individuals with impaired glucose tolerance." (PMID 34131782, 2021). "Global ZnT8-KO mice show reduced islet zinc content, abnormal insulin secretory granule morphology with less insulin crystallization, and impaired glucose tolerance." (PMID 34027899, 2021). "Another study appeared contradictory to our findings, where Rip-cre/smad2fx/fx mice (RIP for “rat insulin promoter”) showed impaired glucose tolerance, impaired insulin secretion, and islet hyperplasia." (PMID 34582892, 2021). "Deterioration of the oral environment (the morbidity of periodontal disease) leads to decreased insulin sensitivity and impaired glucose tolerance." (PMID 34077486, 2021). "With the passage of time, the function of B cells is impaired and the compensatory ability of insulin secretion decreases, thereby resulting in impaired glucose tolerance and even T2DM." (PMID 34122100, 2021). "In overnutrition, macrophage pro-inflammatory signaling and other adipocyte-derived signals, along with excess FA uptake in muscle, lead to impaired insulin signaling and impaired glucose tolerance." (PMID 34888367, 2021). "Prediabetic and diabetic patients, characterized by an impaired glucose tolerance, presented lower insulin levels and a better insulin sensitivity when they restrained their daily eating window to 8 h per day." (PMID 33921979, 2021). "Exercise has been shown to be a valuable primary care strategy for healthy adults to improve insulin sensitivity, and short-term exercise has been shown to improve both insulin resistance and β-cell function in older people with impaired glucose tolerance." (PMID 34442147, 2021). "siRNA knockdown of Meg3 led to impaired glucose tolerance, decreased insulin content and insulin secretion during a glucose challenge." (PMID 34581756, 2021).